RRM2 (ribonucleotide reductase regulatory subunit M2)
Diseases named in the same sentence as RRM2 in open-access papers (continued):
Sharing a sentence is not in itself a finding about the gene and the disease.
tumor (continued). "Acetylation of RRM2 at K95 results in the reduction of the dNTP pool, DNA replication fork stalling, and the suppression of tumor cell growth in vitro and in vivo." (PMID 31324785, 2019). "RRM2 acetylation at K95 suppresses tumor cell growth in vitro and in vivo, and is therefore a potentially attractive strategy for cancer therapy." (PMID 31324785, 2019). "RRM2, ribonucleotide reductase regulatory subunit M2, functions actively in promoting cell invasion, migration, and tumor metastasis." (PMID 31729978, 2019). "Overexpression of RRM2 can promote the proliferation, invasion, and drug resistance of oncogenes and increase the metastasis of tumor cells." (PMID 31673243, 2019). "Immunohistochemistry showed expression of RRM2 in the transplanted tumor tissues of each group, and cell staining was observed in each treatment group." (PMID 31673243, 2019). "We also further investigated the role of RRM2 in tumor growth inhibition in subcutaneous transplanted tumors." (PMID 31673243, 2019). "RRM2 is also involved in the regulation of tumor angiogenesis through downregulation of the anti-angiogenic TSP-1." (PMID 31434359, 2019). "Significant downregulation of RRM2 mRNA and protein expression in the tumor tissues was detected by reverse transcription polymerase chain reaction and immunohistochemistry assay (p<0.05)." (PMID 31673243, 2019). "Immunocytochemical analyses showed that RRM2 protein was almost undetectable in the tumor lesions treated with afatinib in contrast to the control tumor lesions." (PMID 29765556, 2018). "RRM2 can be classified as an oncogene as its overexpression in transgenic mice promoted tumour development." (PMID 30042885, 2018). "To produce a safer and more tumor‐selective oncolytic VACV, we investigated deletion of F4L, a homolog of the RRM2 gene encoding the small subunit of ribonucleotide reductase." (PMID 28289079, 2017). "The F4L‐deleted VACVs are highly attenuated in normal tissues, and since cancer cells commonly express elevated RRM2 levels, have tumor‐selective replication and cell killing." (PMID 28289079, 2017). "Western blot analysis showed elevated expression of both RRM1 and RRM2 in the tumor tissues relative to the normal urothelium." (PMID 28289079, 2017). "Pharmacological inhibition of mTORC1 with rapamycin, mTOR kinase with AZD8055 or protein kinase B with MK2206 resulted in decrease of RRM1 and RRM2 in Rh30 cells both in vitro and in mouse tumor xenografts." (PMID 28507282, 2017). "As a target gene of CREB1, RRM2, except for providing dNTPs for cell proliferation, cooperates with a number of oncoproteins to promote tumor development." (PMID 27801665, 2016). "Here, chemical inhibition of RRM2 with triapine undermined viability and tumour initiating capacity of GBM cells due to increased replication and oxidative stress." (PMID 27845331, 2016). "RRM2 was identified as a tumor promoter in most cancer types and its expression was evidently higher in malignant carcinoma." (PMID 27801665, 2016). "In our previous study, E2F1 was found acting as a tumor driver by activating the transcription of RRM2 in CRC." (PMID 27801665, 2016). "RRM2 expression correlated positively with tumor grade (rho = 0.44, p < 10–5 for cytoplasm and rho = 0.36, p < 10–5 for nucleus)." (PMID 26001082, 2015). "Patients whose tumours are positive for RRM2 and TS have a significantly worse survival with a twofold increased adjusted hazard in patients with NSCLC overexpressing these markers." (PMID 26663950, 2015). "In gemcitabine-resistant tumor cells, RRM2 mRNA is found to be elevated nearly 10-fold relative to that of the parental cells." (PMID 25946136, 2015). "In particular, in agreement with recent reports, patients with underexpressed RRM2 tumours survived longer after radical surgery than those with overexpressed RRM2 tumours." (PMID 26663950, 2015).
tumor (continued). "In the current study, we found that RRM2 expression was rapidly induced by gemcitabine, implying that the upregulation of RRM2 expression in tumor cells is an early event in acquiring resistance to gemcitabine." (PMID 25946136, 2015). "For example, RRM2 plays an important role in regulating expression of the anti-apoptotic protein Bcl-2 and reveal a critical link between RRM2 and Bcl-2 in apoptosis signaling and tumor developing." (PMID 26596768, 2015). "Attenuation of RRM2 expression by let-7b repletion is potentially a promising approach to chemosensitize KRAS mutant tumor cells to gemcitabine." (PMID 25946136, 2015). "In some types of cancer, a high level of RRM2 expression has been reported to be correlated with cellular invasiveness, tumour angiogenesis, metastasis and poor patient outcomes." (PMID 24637958, 2014). "The protein expression of RRM2 was also positively and significantly associated with CD44+/CD24-/low, a tumor stem/progenitor cell biomarker." (PMID 25213022, 2014). "In vivo subcutaneous xenografts of MIA-PaCa2 showed significant tumor suppression when RRM2 siRNA was combined with gemcitabine treatment." (PMID 25499121, 2014). "The combination of PEG-ADI with gemcitabine in vivo yielded significant anti-tumor effects, with the benefit potentially involving the RRM2 induced gemcitabine resistance in PDAC." (PMID 25499121, 2014). "Recently, many studies have demonstrated that RRM2 plays additional roles in determining the malignant potential of tumor cells." (PMID 19250552, 2009). "The changes in the expression of angiogenic factors: TSP-1 and VEGF induced by RRM2 in tumor cells did result in increased angiogenic activity in vitro, as shown by the increased chemotactic activity for endothelial cells." (PMID 19250552, 2009). "Our study demonstrated that overexpression of RRM2 substantially promoted the in vivo growth of tumor cells, and positively affected the overall angiogenic activity of tumor cells." (PMID 19250552, 2009). "Accumulating evidences support RRM2 possesses oncogene-like properties; it plays a potential role in tumor malignancy and metastasis." (PMID 19250552, 2009). "There is limited information concerning the effect of tumoral RRM2 expression and response to gemcitabine in human tumours." (PMID 18414411, 2008). "Several nonspecific inhibitors of ribonucleotide reductase are in fact already in clinical use as chemotherapeutic agents, and more recently, an antisense agent targeting RRM2 has shown potent antitumour activity against a variety of tumours." (PMID 15846300, 2005). "Therefore, targeting RRM2 to inhibit EMT will be an important strategy for inhibiting tumor metastasis." (PMID 40732324, 2025). "Both RRM2 and ADH1B showed excellent diagnostic performance across all cancer types tested except STAD and PAAD, supporting the potential of this pair of genes as pan-cancer diagnostic biomarkers to distinguish between normal and tumor tissues." (PMID 39884577, 2025). "RRM2 is frequently over-expressed as a tumor driver in various malignancies." (PMID 40732324, 2025). "Relative to the other AD samples, both AD5 and the AYA group exhibited higher expression of genes associated with aggressive tumor features and inflammation (e.g., CXCL2, TUBB3, RRM2, and MMP1) and lower expression of differentiation markers and metastatic regulators (e.g., KIT and NCAM1)." (PMID 41374320, 2025). "Notably, RRM2 upregulation correlates with enhanced tumor aggressiveness and chemoresistance, phenotypes that are reversible upon hsa-miR-520a-3p overexpression." (PMID 41568382, 2025). "In the case of its impact on the tumor invasive biological behavioral phenotype, mRNA sequencing was applied to study the effect of its transcriptional level to further explore the downstream effector molecules or pathways of RRM2." (PMID 41333212, 2025). "These miRNAs are likely to function as tumor suppressors by negatively regulating RRM2." (PMID 41357570, 2025).
tumor (continued). "MiR-17-5p inhibits the expression of RRM2, thereby exerting an anti-tumor effect." (PMID 40636359, 2025). "Moreover, RRM2 expression was positively correlated with the infiltration of certain immune cells, suggesting its role in modulating the tumor immune microenvironment." (PMID 41357570, 2025). "The restoration of let-7c-5p expression could potentially inhibit RRM2, thereby suppressing tumor progression in LUAD." (PMID 41357570, 2025). "In tumor tissue, these pathways were significantly deregulated regarding gene and protein expression in two independent datasets, including actionable targets RRM2, GMPS, BCAT1, PYCR2, and NEU1." (PMID 40290517, 2025). "Furthermore, heatmap analysis revealed that TREX1 and RRM2 expression levels were significantly higher in tumor tissues compared to normal tissues, whereas GPX2, DUOX1, and DUOX2 were expressed at lower levels in tumor tissues." (PMID 41346575, 2025). "The overpresentation of RRM2 in tumor tissues also implies its critical biological function, raising questions about whether inhibitors targeting RRM2 could offer new avenues for pan-cancer treatment." (PMID 39884577, 2025). "RRM2, which encodes ribonucleotide reductase, is overexpressed in aggressive basal-like and TNBC, where elevated levels correlate with adverse clinical features including larger tumor burden, lymph node involvement, and disease recurrence." (PMID 41427337, 2025). "Collectively, these data identify RRM2 as a proliferation-associated marker preferentially expressed in activated cytotoxic T cells, implicating its involvement in sustaining immune effector responses within the LUAD tumor microenvironment (TME)." (PMID 41357570, 2025). "Previous studies have shown the important role of RRM2 in tumor cell chemoresistance." (PMID 39343925, 2024). "Moreover, elevated RRM2 expression was indicative of a poor prognosis, as evidenced by IHC staining of tumor samples in conjunction with clinical prognostic data." (PMID 40625451, 2024). "COH29, an inhibitor of RRM2, effectively reduced tumor growth and prolonged survival in vivo." (PMID 39437704, 2024). "Moreover, immunohistochemistry in tumor tissues of iCCA patients revealed an unreported cell membrane localization of RRM2, in contrast to its usual cytoplasmic localization." (PMID 39243109, 2024). "All four individual siRNAs targeting RRM1 or RRM2 caused a reduced viability in the tumor cell lines but not in the normal PO fibroblasts." (PMID 38992100, 2024). "Furthermore, we confirmed through polymerase chain reaction (PCR), western blotting (WB), and immunohistochemistry (IHC) that RRM2 presented high expression in tumor tissues." (PMID 40625451, 2024). "In addition, we conducted a time-dependent ROC curve analysis, which revealed that RRM2 was able to distinguish tumor samples from normal ones and had a satisfactory performance in predicting survival." (PMID 39256879, 2024). "The result indicated that “cell cycle” may play a crucial role in the effect of RRM2 on tumor pathogenesis." (PMID 38635758, 2024). "ATRT is known as a very aggressive tumor, and the high expression of RRM2, which plays a vital role in the cell cycle, suggests that the cell cycle process may be highly activated in this tumor." (PMID 39437704, 2024). "Furthermore, IHC staining images showed stronger RRM2 staining in the tumor compared to PT at the incisal edge." (PMID 40625451, 2024). "Similarly, in mammals, various modes of transcriptional repression or targeting RRM2 result in the suppression of tumor growth, including GBM." (PMID 38612788, 2024). "Furthermore, we identified the expression levels of RRM2 in 33 different tumor and non-tumor tissues based on TCGA datasets." (PMID 38635758, 2024). "One mechanism is that camptothecin-induced DNA damage promotes RRM2 deacetylation by enhancing Sirt2-RRM2 interaction, while the acetylation of RRM2 could disrupt RR assembly, which provides tumor cells with abundant dNTPs for DNA repair and survival." (PMID 38785515, 2024).
tumor (continued). "Moreover, RRM2 expression level was significantly increased in iCCA tumor tissues compared to non-tumor tissues (iCCA cohorts 1–2, P < 0.001)." (PMID 39243109, 2024). "In this study, we previously discovered the role of RRM2 in regulating tumor metastasis." (PMID 39343925, 2024). "In addition, RRM2 and PRC1 were associated with some non-tumor diseases such as sclerocystic ovaries and immunoglobulin A glomerulonephritis, whereas SPAG5 was exclusively associated with pregnancy-related diseases." (PMID 39596028, 2024). "In addition, by collecting clinical MB specimens for polymerase chain reaction (PCR), western blotting (WB), and immunohistochemistry (IHC), RRM2 was confirmed to be highly expressed in tumor tissues." (PMID 40625451, 2024). "Besides, COH29, an inhibitor of RRM2, significantly suppressed tumor growth and prolonged survival of ATRT xenograft mice in vivo." (PMID 39437704, 2024). "Interestingly, limited overlap was found between the two tumor types for their RRM2 or RRM2B hub genes." (PMID 36882565, 2023). "Therefore, future studies should delve into investigating tumor metastasis and the mechanisms governing cell migration under RRM2 inhibition in ATRT." (PMID 38124207, 2023). "RRM2 positivity in HB PDX tumors was well aligned with that of a cell proliferation marker Ki67 (iv–vi vs. x–xii), supporting an association between RRM2 expression and HB tumor malignancy." (PMID 36882565, 2023). "Moreover, compared with traditional tumor markers, RRM2 has higher sensitivity and specificity for the diagnosis of NSCLC, which helps to improve the diagnosis rate." (PMID 37699023, 2023). "The results also confirmed that RRM2 was highly expressed in the tumor tissues (P <0.001)." (PMID 37056349, 2023). "Because HB is very rare, and nearly all children with HB receive neoadjuvant chemotherapy prior to tumor resection, we were unable to obtain matched pre- and post-treatment patient tumor samples to directly determine treatment-induced changes in RRM2 and RRM2B expression." (PMID 36882565, 2023). "The RRM2 expression level in tumor tissues was higher than normal tissues (P <0.001)." (PMID 37056349, 2023). "Both tumor samples showed a markedly higher level of RRM2B than RRM2." (PMID 36882565, 2023). "The results suggested that RRM2 was highly expressed in tumor tissue samples." (PMID 37596700, 2023). "This tumor-promoting effect of RRM2 was observed in multiple other studies." (PMID 37529110, 2023). "Current studies have shown that RRM1 and RRM2 have different effects on tumor progression." (PMID 35204799, 2022). "Immunohistochemical staining on BC tissue samples was used to demonstrate that increased RRM2 was associated with increased tumor size, positive lymph-node status, and increased relapse/metastasis." (PMID 36497242, 2022). "RRM2 is required for tumor growth and functions as a tumor drive." (PMID 36553600, 2022). "Overexpression of RRM2 exhibits the potential to stimulate tumor cell proliferation and migration." (PMID 35248107, 2022). "RRM2 expression was highly associated with immune checkpoint genes and MMR-related genes, indicating that RRM2 may regulate the tumor immune microenvironment to promote tumor growth." (PMID 36518297, 2022). "EGLN1, MIF, PANX1, and RRM2 had higher expression in tumor than in normal samples." (PMID 35311093, 2022). "HELLS, RRM2, and STMN1 expression were positively associated with tumor purity." (PMID 36304446, 2022). "In line with their results, we uncovered that RRM2 was indeed overexpressed in BLCA cell lines and tumor tissues with qRT-PCR, indicating that RRM2 may exert an oncogenic function in BLCA." (PMID 35740608, 2022). "We found that RRM2 expression was predominantly up-expressed in tumor tissues in most tumors." (PMID 35740608, 2022). "Notably, we identified the relation of RRM2 to the tumor microenvironment (TME), ICIs and researched its regulation with immune infiltration and immunotherapy." (PMID 35740608, 2022).
tumor (continued). "RRM2 (ribonucleotide reductase regulatory subunit M2) catalyzes the conversion of ribonucleotides to deoxyribonucleotides, which is the rate-limiting enzyme for DNA synthesis or repair, and plays a crucial role in tumor cell DNA synthesis and proliferation." (PMID 35600868, 2022). "Besides, after suppressing RRM2 expression, the tumor inhibition rate was obviously increased after 48h-treatment with different concentrations of cisplatin." (PMID 35740608, 2022). "and it may act as a carcinogen by modulating the tumor immune microenvironment, which justifies targeting RRM2 as a novel therapeutic approach." (PMID 36518297, 2022). "Similarly, the expression levels of RRM2 and ZWINT have been reported to be associated with tumor formation." (PMID 35028418, 2022). "The tumour-suppressing effect of RRM2 silencing may provide a promising translational target for MM." (PMID 36315425, 2022). "Altogether, our findings suggest that tumor immune escape may be involved in hepatocarcinogenesis mediated by RRM2." (PMID 35911380, 2022). "Remarkably, RRM2 overexpression leads to advanced tumor stages in KICH, KIRP and LUAD." (PMID 35740608, 2022). "In addition to its role as a tumor promoter in various cancers, RRM2 was found to be actively interacting with proteins of RNA viruses such as mouse hepatitis virus and hepatitis C virus." (PMID 35831333, 2022). "In non-neoplastic diseases, researchers have also actively explored RRM2." (PMID 36401415, 2022). "Additionally, G6PD, HELLS, RRM2, and STMN1 were positively associated with higher tumor stage, grade, age, sex, and ethnicity, suggesting an influential contribution to the pathogenesis of HCC." (PMID 36304446, 2022). "Accumulating evidence revealed that RRM2 could be considered a tumor promoter and target for cancer therapy." (PMID 36678539, 2022). "RRM2, the small subunit of ribonucleotide reductase, has been identified as a tumor promoter." (PMID 36518297, 2022). "Therefore, all findings suggest that RRM2 plays an important role in tumorigenesis, tumor progression, and the treatment of cancer." (PMID 36202136, 2022). "We assessed the correlation of RRM2 with tumor stages in TCGA." (PMID 35740608, 2022). "We found that the expression of RRM2 was higher in tumor tissues." (PMID 35898471, 2022). "Among the top 50 of DEGs, RRM2 was closely correlated with DNA replication, cell cycle, lysosomal and proteasome pathways, so we hypothesized that RRM2 may be a key target gene for the anti-tumor effect of PECT on GBM." (PMID 35651787, 2022). "RRM2, a rate-limiting enzyme functioning in the formation of ribonucleotides into deoxyribonucleotides, is very important for DNA replication, which is overexpressed in various tumor progression, leading to poor prognoses." (PMID 35928445, 2022). "Although RRM2 is involved in regulating autophagy pathway and cell cycle arrest, it is unclear whether the two biological phenomena are played a role in the anti-tumor effect of PECT on GBM." (PMID 35651787, 2022). "Additionally, RRM2 upregulation has been involved in resistance to gemcitabine in clinical series of different neoplasms." (PMID 34439352, 2021). "We hypothesized that RRM2 silencing participated in anti-tumor effects by changing tumor microenvironment (TME), the C57BL/6 mice were injected with LV-siRRM2 stable transfected LLC cells." (PMID 33858512, 2021). "Furthermore, we have shown that knockdown of RRM2 enhanced the anti‐tumor efficiency of PD‐1 blockade in RCC." (PMID 34319001, 2021). "We found that RRM2 was also upregulated in EC tumor samples." (PMID 34400640, 2021). "Moreover, the expression of ribonucleotide reductase regulatory subunit M2 (RRM2) is tumorigenic, and the nucleotide-metabolizing enzyme thymine synthase (TS) can independently transform cells in the body and cause tumor formation." (PMID 33952722, 2021). "Many studies have shown that RRM2 plays an important role in tumorigenesis and tumor progression." (PMID 34434213, 2021).